PELP1 (proline, glutamate and leucine rich protein 1)
Description:
Coactivator of estrogen receptor-mediated transcription and a corepressor of other nuclear hormone receptors and sequence-specific transcription factors. Plays a role in estrogen receptor (ER) genomic activity when present in the nuclear compartment by activating the ER target genes in a hormonal stimulation dependent manner. Can facilitate ER non-genomic signaling via SRC and PI3K interaction in the cytosol. Plays a role in E2-mediated cell cycle progression by interacting with RB1. May have important functional implications in ER/growth factor cross-talk. Interacts with several growth factor signaling components including EGFR and HRS. Functions as the key stabilizing component of the Five Friends of Methylated CHTOP (5FMC) complex; the 5FMC complex is recruited to ZNF148 by methylated CHTOP, leading to desumoylation of ZNF148 and subsequent transactivation of ZNF148 target genes. Component of the PELP1 complex involved in the nucleolar steps of 28S rRNA maturation and the subsequent nucleoplasmic transit of the pre-60S ribosomal subunit. Regulates pre-60S association of the critical remodeling factor MDN1. May promote tumorigenesis via its interaction with and modulation of several oncogenes including SRC, PI3K, STAT3 and EGFR. Plays a role in cancer cell metastasis via its ability to modulate E2-mediated cytoskeleton changes and cell migration via its interaction with SRC and PI3K.
Synonyms: MNAR; P160
Tractability: Small molecule: a structure with a bound ligand is known. PROTAC: UniProt records ubiquitination sites on it; ubiquitination databases record sites on it; its protein half-life has been measured; a small molecule that binds it is known.
Gene: Protein-coding gene on chromosome 17 (4,669,774 to 4,704,337, reverse strand). Ensembl gene ENSG00000141456.
Subcellular location: Nucleus, nucleolus; Nucleus, nucleoplasm; Nucleus; Cytoplasm
Subcellular location (Human Protein Atlas): Nucleoli; Nucleoplasm
Pathways (Reactome):
Metabolism of RNA: Major pathway of rRNA processing in the nucleolus and cytosol
Signal Transduction: PTK6 Expression
Gene Ontology:
Molecular function: chromatin binding; protein binding; RNA binding; SUMO binding
Biological process: cellular response to estrogen stimulus; positive regulation of transcription by RNA polymerase II; cleavage in ITS2 between 5.8S rRNA and LSU-rRNA of tricistronic rRNA transcript (SSU-rRNA, 5.8S rRNA, LSU-rRNA); rRNA processing
Cellular component: cytoplasm; euchromatin; MLL1 complex; nucleolus; nucleoplasm; nucleus; rixosome complex
Genetic constraint (gnomAD): Loss-of-function variants: 29 observed, 69.7 expected, observed/expected ratio (o/e) 0.42, 90% interval 0.31 to 0.57. The upper end of that interval is the gene's LOEUF score, 0.57, which puts it in group 2 of 6, group 1 being the genes least tolerant of losing a copy. Missense variants: 1,298 observed, 1,285.8 expected, observed/expected ratio (o/e) 1.01, 90% interval 0.96 to 1.06. Synonymous variants: 640 observed, 545.29 expected, observed/expected ratio (o/e) 1.17, 90% interval 1.1 to 1.25.
Homologues: Orthologues: chimpanzee PELP1 (99% identical), macaque PELP1 (98% identical), rabbit PELP1 (91% identical), pig PELP1 (90% identical), guinea pig PELP1 (89% identical), dog PELP1 (88% identical), rat Pelp1 (87% identical), mouse Pelp1 (87% identical).
Diseases named in the same sentence as PELP1 in open-access papers:
PELP1 is named in the same sentence as 47 diseases in open-access papers, as found by Europe PMC text mining. Sharing a sentence is not in itself a finding about the gene and the disease. The quoted sentences say what the papers report.
breast carcinoma (37 papers, 2008 to 2025). "Breast cancers with a migratory character are caused by PELP1 being localized in the cytoplasm, which increases pro-tumorigenic IKK and NF-κB signaling." (PMID 41463382, 2025). "Breast cancers with migratory characteristics are caused by PELP1 being localized in the cytoplasm, which increases pro‐tumorigenic IKK and NF‐κB signaling." (PMID 37853941, 2024). "PELP1 dysregulation is also implicated in resistance to hormone therapy in breast cancers that are positive for ER expression." (PMID 36351913, 2022). "Namely, PR-B was required for estrogen-stimulated regulation of novel ER/PR/PELP1-target gene sets significantly associated with breast cancer progression to endocrine resistance." (PMID 30652114, 2018). "In the present study, we explored potential associations between PELP1 and E2-dependent ER signaling in breast cancer patients." (PMID 26247365, 2015). "High PELP1 protein expression has been associated with tumor grade, proliferation, node-positive invasive cancer and distant metastases, decreased breast cancer specific survival and disease free survival." (PMID 26247365, 2015). "In summary, this study provides novel information regarding the association of the ER-coactivator PELP1 with estrogens in breast cancer patients." (PMID 26247365, 2015). "Taken together, tumor PELP1 mRNA expression is associated with estrogen levels in breast cancer, suggesting a potentially important role of PELP1 in ER+ breast cancer growth in vivo." (PMID 26247365, 2015). "Our findings add novel information regarding association and, potentially, regulation of the oncogene PELP1 by estrogens in ER+ breast cancer." (PMID 26247365, 2015). "Our results suggest PELP1 to be associated and potentially regulated by estrogens in ER+ breast cancers." (PMID 26247365, 2015). "The finding that PELP1 tumor levels correlated with normal tissue estrogens indicates an association between PELP1 and estrogens in breast cancer patients." (PMID 26247365, 2015). "PELP1 was localized to the cytoplasm in 36% of RPFNA samples from women at high-risk for developing breast cancer, and our in vitro findings show that cytoplasmic PELP1 localization promotes HMEC survival in response to Tam." (PMID 25789479, 2015). "Herein, we tested for PELP1 localization in breast epithelial cells from women at high risk for developing breast cancer and found that PELP1 was localized to the cytoplasm in 36% of samples." (PMID 25789479, 2015). "Elevated PELP1 expression has also been associated with poor outcome in ER positive/luminal-like breast cancer tissue." (PMID 23497172, 2013). "Deregulated PELP1 expression during breast cancer progression is associated with more invasive disease." (PMID 22812534, 2012). "In a subset of human breast tumors, both PELP1 expression and localization are altered; expression during breast cancer progression is associated with more invasive disease." (PMID 22812534, 2012). "To determine whether PELP1 localization is altered during early mammary carcinogenesis, we examined PELP1 localization in 11 randomly selected RPFNA samples from asymptomatic women at high risk for developing breast cancer." (PMID 25789479, 2015). "In breast cancer, PELP1 overexpression has been associated with endocrine therapy resistance." (PMID 26247365, 2015). "PELP1 is being discussed as a potentially targetable proto-oncogene in ER positive breast cancer, associated with rapid tumor growth in xenograft models and high grade as well as node-positivity in human breast cancer." (PMID 23497172, 2013). "In PTX-resistant breast cancer, proline, glutamic acid, leucine-rich protein 1 (PELP1) directly interacts with PFKFB3, leading to breast cancer cells exhibiting high glycolytic characteristics." (PMID 40264038, 2025). "Recent research has shown that the first‐in‐class PELP1 inhibitor SMIP34 is effective at delaying the progression of breast cancer." (PMID 37853941, 2024).
breast carcinoma (continued). "The utility of SMIP34 as a PELP1 inhibitor has been validated in multiple cancer models, including estrogen receptor+ breast cancer, triple-negative breast cancer, and endometrial cancer." (PMID 39258975, 2024). "Changes in the localization of proline-, glutamate-, and leucine-rich protein 1 (PELP1) in the cytoplasm are an oncogenic event that promote breast cancer initiation and progression." (PMID 36892747, 2023). "According to one study, estradiol induces MMP-9 expression in ERα-positive breast cancer cells via PELP1-mediated membrane-initiated signaling." (PMID 37764733, 2023). "Previous work has established that 60-80% of breast cancer cases exhibit abnormal PELP1 expression, which is a predictor of poorer patient outcomes." (PMID 36351913, 2022). "For instance, through the recruitment of HDAC, PELP1 was shown to silence the expression of miR-200 family members and to promote breast cancer metastasis." (PMID 36127329, 2022). "Previous studies have shown that PELP1 is highly expressed in a variety of tumors, such as breast cancer, ovarian cancer, brain cancer, lung cancer, and colorectal cancer, and promotes tumor growth by multiple signaling pathways." (PMID 35053547, 2022). "PELP1’s sub-cellular localization is altered to include the cytoplasm in many breast cancers and is thought to be an effect of increased gene/protein expression." (PMID 36351913, 2022). "PELP1 is involved in the progression of different cancers, including endometrial, salivary, ovarian, pancreas, prostate, colon, lung, and also mainly breast cancers." (PMID 34774800, 2022). "To emphasize the importance of PELP1 in vivo as a link between inflammation and cancer, we generated PELP1 KD clones in 4T1, a murine mammary carcinoma cell line, and then injected them into female nude mice after stimulating with LPS/necrotic HC11 lysate." (PMID 34774800, 2022). "The downregulation of PELP1 enhanced the sensitivity of breast cancer cells to genotoxic agents by suppressing the cell cycle and enhancing apoptosis." (PMID 35682560, 2022). "In breast cancer subtypes, expression of PELP1 is significantly higher in TNBC compared to luminal and HER2-positive BC." (PMID 35205680, 2022). "TFAP2C interactions with PELP1 confer a growth advantage to breast cancer (BC) cells by activating an oncogenic RET signaling thus contributing to BC progression and therapy resistance." (PMID 33269540, 2021). "Co-regulators of ER genomic actions, such as AIB1 (amplified in breast cancer), SRC-1, and PELP1 (proline, glutamate, and leucine-rich protein), have been shown to promote breast cancer metastasis." (PMID 35008370, 2021). "In breast carcinoma cells, under the stimulation of estrogen, PELP1 formed a complex with pRb, which subsequently facilitated CDKs and cyclin D1 induced phosphorylation of pRb, therefore, promoted the progress of cell cycling." (PMID 34257530, 2021). "Examining the levels of PELP-1 in MCF7 cells revealed that these cells had high levels of protein expression as compared to a panel of other ER+ breast cancer cell lines." (PMID 33473257, 2020). "We identified AIB1 as a novel binding partner of cytoplasmic PELP1 in both normal and breast cancer cell models." (PMID 30652114, 2018). "We recently reported that cytoplasmic PELP1/AIB1 complexes function to promote advanced breast cancer phenotypes, specifically the outgrowth of CSCs." (PMID 30652114, 2018). "Similar mechanisms have been revealed in breast cancer cells where PELP1 has been shown to be a critical mediator of estrogen-induced MAPK activation via c-Src." (PMID 29112114, 2017). "Prior studies have shown that cytoplasmic proline, glutamic acid and leucine rich protein 1 (PELP1) promotes Tam resistance in breast cancer cell lines." (PMID 25789479, 2015). "Prior studies in ER+ breast cancer cell line models have shown that PELP1-cyto promotes activation of ERK1/2 and Akt signaling through EGFR to promote resistance to Tam." (PMID 25789479, 2015).
breast carcinoma (continued). "Although previous studies have shown that PELP1 functions as an oncogene that is deregulated in breast cancer, little is known about the prognostic significance of PELP1 in TNBC." (PMID 26472563, 2015). "PELP1 is frequently overexpressed in breast cancer, and altered localization to the cytoplasm has been described in approximately 50% of PELP1-positive breast tumors." (PMID 25789479, 2015). "The proto-oncogenic functions of PELP1 involve different cellular processes including epigenetic modifications leading to ER transactivation and breast cancer progression." (PMID 26247365, 2015). "In order to elucidate associations between PELP1 and estrogens in vivo, we performed Spearman correlations of tumor PELP1 mRNA with E1, E2 and E1S levels in tumor, normal breast tissue and plasma from breast cancer patients." (PMID 26247365, 2015). "Several studies also proposed PELP1 as a prognostic biomarker in hormone-related cancers, including endometrial, ovarian, colorectal, and luminal-type breast carcinomas." (PMID 26472563, 2015). "Vadlamudi and colleagues were the first to demonstrate altered PELP1 localization in human tumors and show that cytoplasmic PELP1 signaling promotes Tam resistance in ER+ breast cancer cell line models." (PMID 25789479, 2015). "We found that MMP-3 expression, which is regulated by PELP1 in MDA-231 breast cancer cells, was upregulated in PELP1-cyto HMECs." (PMID 25789479, 2015). "Further evidence supporting a role for PELP1 as a biomarker of breast cancer initiation would provide a strong rationale for these larger and longer-term studies." (PMID 25789479, 2015). "We analyzed PELP1 mRNA expression levels in breast cancer and normal tissue samples and potential connections to ER- and postmenopausal status of the patients." (PMID 26247365, 2015). "In this clinical study, PELP1 mRNA expression levels in matched malignant and normal breast tissue from breast cancer patients were analyzed and correlated with E1, E2 and E1S levels." (PMID 26247365, 2015). "Recent results based on RNA-sequencing have demonstrated that PELP1 regulates a number of genes involved in estrogen signaling, breast cancer progression and RNA splicing." (PMID 26247365, 2015). "PELP1 seems to be of importance in breast cancer, due to an involvement in hormone therapy response and resistance." (PMID 23497172, 2013). "PELP1 deregulation occurs within several hormone-responsive malignancies including breast cancer, ovarian cancer and prostate cancer." (PMID 22812534, 2012). "Co-regulator PELP1 is shown to function as a proto-oncogene and was recently demonstrated to be an independent prognostic marker for poor breast cancer survival." (PMID 22812534, 2012). "Our results indicate that functional PELP1 axis is necessary for optimal proliferation of breast cancer cells and plays a critical role in modulating epigenetic marks on histone tails needed for proliferation in vivo." (PMID 22812534, 2012). "In a preclinical study of ERα-positive breast cancer patients, PELP1 expression was identified as an independent prognostic biomarker in assessing clinical outcome; elevated expression associated positively with poor prognosis." (PMID 22812534, 2012). "MCF7, a breast cancer cell line, when synchronized to G1 phase by serum starvation, PELP1 had prominent nuclear localization with negligible nucleolar localization." (PMID 21695158, 2011). "In addition, the histological expression patterns of PELP1 in LUAD were identical to those in breast cancer cases, in which, PELP1 was reported to play a critical role in the initiation, development, and treatment resistance of the tumors." (PMID 34257530, 2021). "Indeed, PELP1 itself is emerging as a viable therapeutic target and biomarker for women with breast cancer." (PMID 30652114, 2018).
breast carcinoma (continued). "PELP1-driven signaling to nuclear transcription factors, including SRs, represents a likely mechanism by which these molecular partners function together to drive SR+ breast cancer progression, breast CSC biology, and therapy resistance." (PMID 30652114, 2018). "However, altered localization of PELP1 to the cytoplasm is an oncogenic event that promotes breast cancer initiation and progression." (PMID 30652114, 2018). "We therefore hypothesized that cytoplasmic PELP1 drives breast cancer initiation and epithelial cell survival though an ER-independent mechanism involving ERRγ." (PMID 25789479, 2015). "In addition to ERRγ, proline, glutamic acid and leucine-rich protein-1 (PELP1), a nuclear receptor co-activator protein, has been shown to promote Tam resistance in invasive breast cancer cell line models." (PMID 25789479, 2015). "PELP1 expression has been suggested to play a significant role in both ER+ and ER- breast cancer." (PMID 26247365, 2015). "We hypothesize that estrogens influence PELP1 mRNA expression in breast tumor tissue, suggesting a potential important role of PELP1 in ER+ breast cancer growth in vivo." (PMID 26247365, 2015). "Although PELP1 is known to be regulated by estrogens in vitro, its association with estrogen levels within the tissue of breast cancer patients has not previously been assessed." (PMID 26247365, 2015). "Similar to PELP1, ERRγ promotes breast cancer progression both in vivo and in vitro." (PMID 25789479, 2015). "PELP1 expression is upregulated by ER in breast cancer cells in vitro." (PMID 26247365, 2015). "However, ER signaling is complex and involves multiple coregulatory proteins including PELP1, an ER coactivator that is dysregulated in breast cancer." (PMID 26247365, 2015). "However, the potential role of PELP1 as an executor of estrogens pro-carcinogenic effects in human breast cancer remains to be verified." (PMID 26247365, 2015). "Similarly, expression of the ER coregulator PELP1 is deregulated in metastatic breast tumors, and PELP1 protein expression is an independent prognostic predictor of breast cancer-specific survival and disease-free survival." (PMID 22295247, 2012). "Here we utilized pargyline to examine whether it has the potential to restore altered epigenetic changes in PELP1-driven breast cancer." (PMID 22812534, 2012). "PELP1 is also recently identified as a proto-oncogene that exhibits aberrant expression in many hormone-related cancers and is a prognostic indicator of shorter breast cancer-specific survival and disease-free intervals when over-expressed." (PMID 21695158, 2011). "Finally, this brings into question the consequence of robust PELP1 overexpression observed in ERα positive breast cancers, as well as many hormonal cancers, wherein PELP1 oncogenic function may extend beyond ribosome synthesis and into SR coactivation." (PMID 36351913, 2022). "Therefore, PELP1 is postulated to function independently of ERα in breast carcinoma cells." (PMID 26472563, 2015). "To test the hypothesis that cytoplasmic PELP1 promotes breast cancer initiation we would need to examine PELP1 localization in 300 samples to obtain 85% power to detect a difference in the incidence rate for a new breast cancer of 0.60 vs 0.44, assuming a one-sided alpha of 0.05." (PMID 25789479, 2015). "The hsa-miR-145-5p interactions with estrogen receptors, PELP1, and SRC highlight its implications in, e.g., breast cancer progression and treatment." (PMID 40362695, 2025). "PELP1 interacts with p85 subunit of PI3K and also with EGFR in breast cancer (BCa) cells, activating c-Src." (PMID 41463382, 2025). "PELP1 directly bound to the promoter sequences of miR-200a and recruited HDAC2, which decreased the expression of miR-200a in breast cancer cells." (PMID 35682560, 2022). "This study suggests that the PELP1/SETDB1 axis play an important role in aberrant Akt activation and serves as a novel target for treating endocrine therapy resistance in breast cancer." (PMID 35395812, 2022).